DCX (doublecortin)
Diseases named in the same sentence as DCX in open-access papers (continued):
Sharing a sentence is not in itself a finding about the gene and the disease.
Zinc deficiency (1 paper, 2020). A deficiency of the essential metal Zinc; an essential cofactor for many enzymes. "Zinc deficiency has been shown to reduce the levels of doublecortin (DCX) expression, a marker of neuronal differentiation." (PMID 33255662, 2020). "In zinc-deficient mice, DCX-positive cells also reduced process formation and neuronal branching, which suggested that zinc deficiency actually impairs neurogenesis by reducing neural differentiation." (PMID 33255662, 2020).
tumor (60 papers, 2008 to 2025). "Higher proportion of DCX + cells (stratification based on 75th quantile) in tumour stroma in our cohort were associated with shorter patient survival." (PMID 39232464, 2024). "In transgenic models of prostate cancer (PCa), doublecortin-positive neural progenitors from the subventricular zone have been shown to traverse the blood-brain barrier and infiltrate tumors, with their density correlating positively with tumor invasiveness and recurrence risk." (PMID 41163091, 2025). "Elevated expression of neuroprecursor markers such as nestin and doublecortin within the tumor parenchyma suggests that the TME supports neuronal maturation." (PMID 41163091, 2025). "In murine models, DCX+ progenitors infiltrate tumors, where they differentiate into tyrosine hydroxylase-positive adrenergic neurons, and genetic ablation reduces tumor growth and suppresses metastasis." (PMID 40243726, 2025). "DCX, involved in neuronal migration, is expressed in only rare tumour cells and appears unrelated to invasion." (PMID 41179304, 2025). "Further, we find that stromal DCX + cells also express other markers for neural progenitor cells, in both luminal-like and basal-like tumours, supporting a neural phenotype of these stromal cells." (PMID 39232464, 2024). "The depletion of DCX+cells also reduced the incidence of tumor lesions, and with the addition of DCX+neural precursor cells, tumor growth accelerated." (PMID 39119085, 2024). "At the tumor site, DCX-expressing neural progenitor cells differentiate into adrenergic neurons to promote tumorigenesis." (PMID 38334648, 2024). "After migration, these DCX + cells in the TME differentiate to form maturing neurons contributing to tumour progression." (PMID 39232464, 2024). "Kaplan–Meier analysis showed that forty-five days post tumor cell implantation, DCX knockdown mice treated with TMZ, and irradiation individually survived significantly longer than the control groups." (PMID 39719558, 2024). "Depletion of these doublecortin-positive neural progenitor cells abolishes tumor initiation and progression." (PMID 38375479, 2024). "Genetically removing DCX+ cells inhibits early tumor development in mouse models, while transplanting DCX+ neural progenitors promotes tumor growth and metastasis." (PMID 37566075, 2023). "No neural cells were found in the microenvironment of BPDCN patient samples, but tumor cells showed expressions of DCX (11/15) and UCHL-1 (15/15), which are neural markers involved in neurogenesis." (PMID 35954431, 2022). "H&E staining and immunohistochemistry analysis showed decreased DCX-positive cell expression compared to tumor control, which signifies the neural plasticity impairments in the chemotherapy-treated tumor mice." (PMID 34643772, 2021). "On the other hand, the frequency of NES+ cells on the margin and within the tumour were reversely correlated with DCX+ cells in the margin." (PMID 34948016, 2021). "MTX + 5-FU treatment after the onset of tumor development led to a suppression of DCX+ cells in the SGZ by 40% in both transgenic and wild-type mice, confirming earlier findings." (PMID 34884513, 2021). "Instead, the tumor cells themselves turned out to express neural markers; 11/15 cases stained for DCX (6/11 at high score level) and all cases were positive for UCHL-1 (6/15 cases at high level)." (PMID 34572907, 2021). "Immunostaining of invasive cell markers showed lower CD31 and EGFR expression in DCX NLS2-mut tumor." (PMID 32050972, 2020). "A panel of neuronal genes, such as DCX, NEURONG2, MAP2, NEUROD1, were upregulated with FTT treatment for 2 or 10 days, while tumor associated genes downregulated." (PMID 30837577, 2019). "Simultaneous expression of DCX with SPARC and semaphorin3B indicated a greater risk to patients' survival, thus proposing a direct link between tumor invasion and patient's survival." (PMID 28701917, 2017).
tumor (continued). "Another study suggested that DCX is phosphorylated by Rho-kinase and that this phosphorylation is correlated with in vitro tumor cell migration, as well as in vivo invasion and progression." (PMID 26764906, 2016). "The Nilo2+ cells surrounding the GFP-tumor were also DCX+ cells, indicating that they correspond to bona fide neuroblasts." (PMID 22957072, 2012). "These hypointense signals increased and accumulated surrounding the tumor and corresponded to endogenous Nilo2+ DCX+ cells." (PMID 22957072, 2012). "To date, the presence of DCX in human NB has been evaluated only by real-time RT-PCR in tumor samples, and by Western blot (WB) analysis in SH-SY5Y cell line." (PMID 18230156, 2008). "A recent study on prostate cancer used lineage tracing of doublecortin-positive neural progenitor cells from the subventricular zone of the brain to examine whether tumor innervation can originate from the CNS." (PMID 38375479, 2024). "Therefore, to avoid any potential contribution of DCX positivity coming from the tumour cells, we focus on stromal DCX expression." (PMID 39232464, 2024). "This is achieved through the oscillation of DCX+ neural progenitor cells in the subventricular zone, which results in the disruption of the blood–brain barrier and efflux of DCX+ cells into the bloodstream, where they infiltrate and colonise the tumour and generate nascent neurons." (PMID 36675991, 2022). "Our results showed that only a small subset of DCX positive (DCX+) cells was present in the tumour." (PMID 34948016, 2021). "The percentage of DCX+ cells in Ast2 tumor was ~1% of total cells." (PMID 33923449, 2021). "We anticipate that a panel of markers, such as BPTF, TMCO3, CUX2, combined with classic markers: PHOX2B, TH, DCX, will prove valuable in a variety of clinical settings, including the assessment of tumor, drug resistance, residual disease monitoring and prediction of recurrence." (PMID 29467591, 2018). "In addition, Nilo2-mGNPs identified bona-fide neuroblasts in subependymal patches on the lateral ventricle and the anterior horn of the contralateral ventricle with respect to tumor localization, since all the Nilo2+ cells were also DCX+." (PMID 22957072, 2012). "Our GD2 positive cell preparations were enriched in CD56+ and NB84+ mononuclear NB cells, showed the same genetic aberration as the primary tumor cells, and expressed NB-specific genes, such as TH, GD2 synthase, Phox2b, ELAV4 and DCX, at the same levels as primary tumor cells." (PMID 22253825, 2012). "Moreover, the intra-cranially growing tumor derived from shFABP7 transduced cells showed a significantly lower DCX expression than in scrambled NS (***p<0.001), suggesting that FABP7 play a role in the invasion rather than in the proliferative process." (PMID 23284888, 2012). "They displayed low levels of Ki67, Olig2, and DCX and higher levels of the mature neuronal marker NeuN, suggesting that overexpression of Foxr2 alone may lead to lesions that harbor differentiated cells and fewer proliferative or stem-like tumor cells." (PMID 39495206, 2025). "Importantly, DCX and VAChT were found in the tumor bulk, where they displayed co-localization." (PMID 39717507, 2025). "Interestingly, DCX was highly expressed in both high-grade and low-grade invasive tumours." (PMID 34948016, 2021). "Effects of DCX high expression, knockdown, mutation, and/or deletion of putative NLS sites were probed via Boyden’s invasion assay and wound healing migration assays, and viability was detected by CCK8 assays in-vitro, while xenograft tumor model was performed in nude mice." (PMID 32050972, 2020). "Western blotting highlighted positive staining for DCX and INA in tumor samples, and a lower expression of the mature neural marker NeuN, strongly suggesting the presence of immature neurons." (PMID 39717507, 2025).
tumor (continued). "Collectively, these results highlighted the neural-oriented transcriptional program of a BPDCN tumor with the expression of well-known neural genes (EDN3, NLGGN4X, UCHL-1, and DCX) and the activation of neural receptor genes (Ach receptors)." (PMID 35954431, 2022). "In order to examine how the neuroblast population was changed in response to tumor proximity to the SVZ, we performed immunohistochemical staining for doublecortin (DCX+), a widely used marker for migratory neuroblasts." (PMID 34268110, 2021). "We also evaluated the correlations between the expression of DCX, OLIG2, and NES genes at a single-cell level in the population of cells derived from the tumour tissue to show the potential relation of these genes." (PMID 34948016, 2021). "Although DCX was detected in most samples, DCX+ cells were only a small subset of the GBM’s cell population, both in tumours and margins." (PMID 34948016, 2021). "The neoplasm was mainly composed of round, uninucleate cells with hyperchromatic nuclei, which were immunopositive for OLIG2, doublecortin, MAP2, synaptophysin, and vimentin, indicating components of both oligodendroglial and neuronal differentiation." (PMID 34977226, 2021). "In xenograft models, tumors with doublecortin positive neural progenitors contributed to tumor progression dramatically and selective depletion of DCX positive cells reduced the tumor growth." (PMID 33572108, 2021). "In the future, we will analyze the relationship between the NB5 assay and prognosis and explore the relationship between tumor relapse and PHOX2B, TH, DDC, CHGA, and DCX expression." (PMID 34055604, 2021). "Thus, finding different pathways through which DCX conjugates with other proteins to stabilize the MT and its activities in the actin cytoskeleton should be prioritized as these pathways may provide insights for inhibiting tumor progression." (PMID 28701917, 2017). "Because the Ara-C experiment cannot be performed in human or non-human primates, we applied this treatment in adult mouse brain to reveal that c-Myc is highly expressed in DCX-positive population within SVZ, which has intimate contact with GBM1 tumor." (PMID 23875172, 2013). "Interestingly, the infiltrated macrophages were more abundant in DCX-specific and mixed region than in SOX2-specific region, indicating different tumor immune microenvironment among neuroectodermal subtypes." (PMID 36936909, 2023). "Additionally, a sub-population of neural progenitor cells expressing doublecortin (DCX) protein and normally present in the region of the brain where neurons are renewed (sub-ventricular zone) was found outside the brain in the tumor microenvironment." (PMID 35441960, 2022). "Tumor bearing mice treated with saline did not exhibit any differences in rates of DCX+ expression in the SGZ relative to wild-type control mice, indicating that the presence of cancer on its own did not affect hippocampal cell proliferation rates." (PMID 34884513, 2021). "Tumor-implanted mice that received RT + aPD-1 treatment also showed permanent depletion of DCX + neuroblasts in the SGZ which was not prevented by elimination of microglia by PLX5622 or by aCSF1R (P < 0.01)." (PMID 33658642, 2021). "Although most of the cells expressing DCX within the tumour were marked as non-cancerous, four subpopulations were marked as GBM origin." (PMID 34948016, 2021). "These annotations were used to predict the role of DCX, OLIG2, and NES in tumour biology." (PMID 34948016, 2021). "The BPDCN microenvironment resulted negative for neural markers but, surprisingly, the tumor cells themselves were positive for the 2 progenitor neural markers: DCX and UCHL-1, in 11/15 (73.3%) and 15/15 (100%) cases, respectively." (PMID 34572907, 2021).
tumor (continued). "Even though DCX-NLS2 tumor showed a higher amount of DCX IHC intensity, immunofluorescence showed a lesser amount of nuclear DCX in the DCX NLS2-mut tumor, and those cells expressing nuclear DCX were displaced mainly to the core of the tumor body." (PMID 32050972, 2020). "In addition to SP1, tumor supporters such as E2F3a, BAX, BMI-1, DCX and Reelin are also targeted by miR-128." (PMID 24959930, 2014). "We also evaluated whole sections of five luminal and five basal-like tumour tissues not included in the cohorts for IMC analysis by IHC staining for DCX, and we could only identify a few cancer cells with weak DCX positivity." (PMID 39232464, 2024). "Chemotherapy-treated tumor-bearing mice showed cytokine deregulation explained by increased levels of IL-6, TNF-α, RANTES (regulated upon activation, normal T cell expressed and presumably secreted), and impaired neurogenesis indicated by the decreased number of DCX positive neurons." (PMID 34643772, 2021). "A negative correlation seems not to support the existence of the DCX-NES complex in the tumour." (PMID 34948016, 2021). "We did not observe any GFP-/DCX+ cells migrating to the tumor site (data not shown)." (PMID 34268110, 2021). "Since the expression DCX and UCHL-1 may increase the ability of BPDCN tumor cells to disseminate to distant organs, globally worsening patient outcome, both genes, as already suggested for NLGN4X and EDN3, may be regarded as possible therapeutic targets to arrest BPDCN dissemination." (PMID 34572907, 2021). "Moreover, no particular pattern emerged when analysing DCX+ cells relative position to the tumour margin." (PMID 34948016, 2021). "Moreover, invasive tumours have been shown to express higher levels of DCX when compared to circumscribed tumours; no expression in normal brain tissue surrounding the tumour was found." (PMID 34948016, 2021). "However it is not known whether DCX is expressed in all the different cell-types (S, N and I) composing the tumor or it is a characteristic of some of them, and whether its interacting protein LIS1 is also expressed in the human NB." (PMID 18230156, 2008). "Our data also support the notion that there is a set proportion of cells expressing DCX/NES/OLIG2, regardless of treatment, guided by tumour plasticity." (PMID 34948016, 2021). "Consistent with the behavioral data, there was an absence of a tumor effect on BDNF gene expression and DCX + cells (approximate measure of neurogenesis)." (PMID 28811490, 2017). "Endoxifen-induced tumours expressed GFAP, nestin, Sox2, Olig2, PDGFRa and doublecortin (Fig. 5E1-J1), and were indistinguishable from tumours generated by Adeno-Cre or Adeno-GFAP-Cre injection and as shown in Fig. 5E2-J3." (PMID 26704996, 2016). "Although cells expressing DCX lacked this correlation, there was a strong negative correlation between the frequency of DCX+ cells in the margin and the frequency of NES+ cells both in tumour and margin sites." (PMID 34948016, 2021). "On the other hand, the expression of CD166, CD133, CD44, A2B5, CD56, NGFR and DCX seemed to be higher in UA cells, but also not statistically significant, while the expression of CD9, Nestin, GFAP, CD24, PDGFRb, PDGFRa, MAP2, TUBIII, S100 were consistently high in both UA and tumor core samples and." (PMID 27605047, 2016).
cancer (22 papers, 2008 to 2025). A tumor composed of atypical neoplastic, often pleomorphic cells that invade other tissues. "These cells express the doublecortin (DCX) surface marker for progenitor cells, which has been found to be expressed at higher levels in individuals with high-risk cancers." (PMID 36980690, 2023). "Unstable interactions between DCX and MTs destabilizes cytoskeletal organization leading to disorganized movements of cells, a process which may be implicated in the uncontrolled migration of cancer cells." (PMID 28701917, 2017). "Interestingly, DCX may also be implicated in the development of cancer cells due to its significance in the migration of neuroblasts." (PMID 28701917, 2017). "When DCX is phosphorylated on its serine residues, it tends to leave the MTs and shifts toward f-actin to aid the polymerization of the actin filaments and improve migration, another process that may be implicated in the migration of cancer cells." (PMID 28701917, 2017). "The modification of tubulin configuration is a reason for cancer resistance to apoptosis because cancer cells can switch the polymerization of the microtubule by enhancing the expression of DCX." (PMID 34513834, 2021). "DCX in the “cancer” identified cells was expressed in these clusters, identified according to the transcriptomics signatures specific for oligodendrocytes, undifferentiated, and proliferative cells." (PMID 34948016, 2021). "Recent studies have suggested that NPCs [doublecortin (DCX) +] are transported from the CNS (SVZ) into circulation after blood-brain barrier (BBB) disruption during cancer development." (PMID 33392191, 2020). "At 12 weeks, progenitor GSCs gave rise to tumors expressing mainly the progenitor marker ASCL1 and small populations of cancer cells expressing the neuronal marker DCX or the astro-mesenchymal marker CD44." (PMID 32641768, 2020). "The crucial roles of DCX in the development and migration of neuroblasts make it a vulnerable target for cancer cells." (PMID 32050972, 2020). "The data reviewed above suggest that DCX regulates cancer cells mobility and invasion of adjacent tissues by remodeling the cytoskeletal network in response to signals influencing the survival of cancer cells." (PMID 28701917, 2017). "In this review, we have assembled the features of DCX and highlighted its importance in the CNS as well as cancers to identify research gaps and project new research areas for the benefit of cellular dynamics and neurogenesis." (PMID 28701917, 2017). "During the past few years, we noticed a decrease in research about DCX, this is a major concern as we believe there is more to be explored in this field, most especially its roles in cancer cell initiation." (PMID 28701917, 2017). "We will also describe the implications of MT stabilization by phosphoregulation of DCX in cancer cell migration and possible problems that define the field." (PMID 28701917, 2017). "DCX is significantly expressed in a variety of cancers even when it is regarded as a neuron-specific MAP." (PMID 28701917, 2017). "GTP to GDP hydrolysis mediated by DCX promotes cancer cell survival." (PMID 34513834, 2021). "To better understand the function of DCX, we opted for the single-cell approach, which allowed annotating the cells as “cancer” and “normal” according to the number of GBM specific copy number variations (CNV) prediction based on transcriptomics of single cells." (PMID 34948016, 2021). "We reasoned that DCX co-expression signature may shed information on NUC control in NB, as the expression of DCX mRNA was a specific trait of cancers of NE origin, including NB (top and S1A, and S3A)." (PMID 33658318, 2021). "Recent studies demonstrated that DCX may be responsible for cancer metastasis and uncontrolled migration of cancer cells." (PMID 34572907, 2021). "Several studies suggest that DCX is involved in cancer metastasis." (PMID 28701917, 2017).